TRIM9 (tripartite motif containing 9)
Diseases named in the same sentence as TRIM9 in open-access papers (continued):
Sharing a sentence is not in itself a finding about the gene and the disease.
colorectal cancer (1 paper, 2024). A primary or metastatic malignant neoplasm that affects the colon or rectum. "Under the stimulation of netrin‐1, TRIM9 promotes the malignant proliferation of colorectal cancer cells and reduces the prognosis of patients." (PMID 38263865, 2024).
endometrial cancer (1 paper, 2023). Primary or metastatic malignant neoplasm involving the endometrium (mucous membrane that lines the endometrial cavity). "In this study, the expression levels of TRIM9 in tumor tissues were found to be lower than those in normal tissues, and it was found to be a risk factor for poor endometrial cancer prognosis." (PMID 36611207, 2023).
glioma (1 paper, 2024). A benign or malignant brain and spinal cord tumor that arises from glial cells (astrocytes, oligodendrocytes, ependymal cells). "In addition, auto-antibodies against TRIM9/SPRING and TRIM67/TNL have been described as a potential high-risk paraneoplastic biomarker, and TRIM67/TNL is associated with higher cell motility and reduced cell adherence in glioma cells." (PMID 39205302, 2024).
injury (1 paper, 2020). Damage inflicted on the body as the direct or indirect result of an external force, with or without disruption of structural continuity. "Their findings suggest that TRIM9 is essential for resolving NF-kB-dependent neuroinflammation to promote recovery and repair after brain injury and that manipulating TRIM9 expression may represent an attractive immunomodulatory therapeutic target." (PMID 33049931, 2020).
Lewy body disease (1 paper, 2021). "The expression of this brain-specific E3 ubiquitin ligase Trim9 is decreased in aged mice, and is repressed in affected brain areas of Lewy body disease." (PMID 33670299, 2021).
lung carcinoma (1 paper, 2018). "TRIM9 E3 ligase knockdown in human lung cancer tissues and cell lines reduces Bcl-2 expression while it activates the caspase-7 and caspase-9." (PMID 29479529, 2018). "TRIM9 and ZBTB38 are other E3 ligases where knockdown of these resulted in caspase-9 and 7 activations in human lung carcinoma and C2C12 cells, respectively." (PMID 29479529, 2018).
pancreatic cancer (1 paper, 2025). "By intersecting the ubiquitination-related genes with pancreatic cancer-associated genes, we identified a gene, TRIM9." (PMID 41050689, 2025). "In conclusion, our study identifies TRIM9 as a key regulator of HNRNPU stability through K11-linked ubiquitination in pancreatic cancer." (PMID 41050689, 2025). "By further investigating the role of TRIM9 and its associated pathways in pancreatic cancer, we may uncover new therapeutic strategies to target ubiquitination-related processes and improve patient outcomes." (PMID 41050689, 2025). "Furthermore, we used GWAS (genome-wide association studies) and SMR (Summary-data-based Mendelian Randomization) analyses to examine the genetic associations between TRIM9 and pancreatic cancer susceptibility." (PMID 41050689, 2025). "Our findings also suggest that targeting TRIM9 or its associated ubiquitination machinery could offer novel therapeutic opportunities for pancreatic cancer." (PMID 41050689, 2025). "In the MIAPaca-2 pancreatic cancer cell line, overexpression of TRIM9 led to a reduction in the protein level of HNRNPU." (PMID 41050689, 2025). "TRIM9 was found to be a protective factor for pancreatic cancer in both the bbj_a_140 and ebi-a-GCST90018673 datasets, and it exhibited colocalization with genes such as TMX1 and PYGL." (PMID 41050689, 2025). "In the GSE287735 and GSE62452 datasets, TRIM9 was found to be downregulated in pancreatic cancer tissues compared to normal tissues (p<0.001, p<0.01)." (PMID 41050689, 2025). "This represents a novel regulatory mechanism by which TRIM9 modulates the stability of a key oncogenic protein in pancreatic cancer." (PMID 41050689, 2025). "By examining the ubiquitination-dependent regulation of TRIM9 and its potential impact on HNRNPU stability, this study contributes to the growing body of knowledge on the molecular mechanisms underlying pancreatic cancer." (PMID 41050689, 2025). "Both WB and PCR results showed that TRIM9 expression was significantly downregulated in pancreatic cancer tissues compared to adjacent normal tissues." (PMID 41050689, 2025). "To further explore the role of TRIM9 in pancreatic cancer, we conducted expression and prognosis analyses." (PMID 41050689, 2025). "Our study contributes to this gap by providing evidence that TRIM9 exerts its effects on pancreatic cancer through its interaction with HNRNPU." (PMID 41050689, 2025). "To verify the role of TRIM9 in pancreatic cancer, we first performed Western blot (WB) and PCR analyses on clinical samples." (PMID 41050689, 2025). "Given the essential role of TRIM9 in modulating HNRNPU stability and tumor progression, targeting TRIM9-mediated ubiquitination could provide a more specific approach to modulate protein degradation pathways in pancreatic cancer." (PMID 41050689, 2025). "Our findings suggest that TRIM9-mediated ubiquitination represents a novel mechanism for regulating protein stability in pancreatic cancer and may offer new therapeutic avenues for targeting ubiquitination-related pathways." (PMID 41050689, 2025). "Similarly, in pancreatic cancer cell lines, TRIM9 expression was also reduced compared to normal pancreatic cell lines, with the lowest expression observed in the MIAPaca-2 cell line and relatively higher expression in the Panc-1 cell line." (PMID 41050689, 2025). "While previous studies have investigated the role of TRIM9 in cellular homeostasis, its role in cancer, particularly in pancreatic cancer, had not been well characterized." (PMID 41050689, 2025). "To test this hypothesis, we employed a variety of computational and experimental approaches, including single-cell RNA sequencing (scRNA-seq), spatial transcriptomics, and transcriptomic data analysis, to explore the expression patterns of TRIM9 and HNRNPU in pancreatic cancer." (PMID 41050689, 2025).
psychosis (1 paper, 2020). "Two of those novel interactors, ATL1 and TRIM9 are shown to be associated with cognitive performance and psychosis respectively through GWAS." (PMID 32973177, 2020).
schizophrenia (1 paper, 2021). A major psychotic disorder characterized by abnormalities in the perception or expression of reality. "In the same manner, 60 of 66 sites dEd in schizophrenia were concentrated in the TRIM9 and SNHG14 genes." (PMID 34535545, 2021).
triple-negative breast carcinoma (1 paper, 2025). An invasive breast carcinoma which is negative for expression of estrogen receptor (ER), progesterone receptor (PR), and human epidermal growth factor receptor 2 (HER2). "METTL14 activates miR-29c-3p through m6A and regulates the ubiquitination of pyruvate kinase isoform M2 (PKM2) mediated by the tripartite motif containing 9 (TRIM9), driving aerobic glycolysis of glucose and promoting the progression of triple-negative breast cancer (TNBC)." (PMID 41256854, 2025).
tumor (9 papers, 2015 to 2025). "Integrated analyses highlight TRIM9 as a tumor suppressor and prognostic biomarker, mediated via ubiquitination-dependent regulation of HNRNPU stability." (PMID 41050689, 2025). "In this study, we identified TRIM9 as a critical player in regulating the stability of HNRNPU, a key RNA-binding protein involved in tumor progression, via K11-linked ubiquitination." (PMID 41050689, 2025). "Further in vivo experiments demonstrated that overexpression of TRIM9 reduced the tumor volume and weight in nude mice, while co-overexpression of HNRNPU rescued this effect." (PMID 41050689, 2025). "In the TCGA cohort, we observed differential expression of TRIM9 across tumor stages, with TRIM9 expression decreasing as tumor grade increased." (PMID 41050689, 2025). "Future studies incorporating single-cell proteomics and spatially resolved proteomics will further enhance our understanding of the dynamic interactions between TRIM9, HNRNPU, and other tumor-associated factors." (PMID 41050689, 2025). "TRIM9 is a key protein that regulates the inactivation of ubiquitination of tumour suppressor genes." (PMID 38263865, 2024). "Given the essential role of Smad2/3 signaling in TRIM9-induced tumor progression, it should be feasible to suppress Smad2/3 molecule to improve the outcome of chemotherapy in TRIM9-high patients." (PMID 37249822, 2023). "Subsequent functional experiments provided novel evidence that TRIM9 exhibited tumor suppressive effects through the interaction with ZEB1." (PMID 37124931, 2023). "Clinical tumor tissue samples combined with cancer cell line models were utilized to explore the TRIM9 expression pattern." (PMID 37124931, 2023). "This study concluded that TRIM9 was a tumor suppressor that interacted with ZEB1 and accelerated ZEB1 protein degradation via the ubiquitin-proteasome pathway (UPP)." (PMID 37124931, 2023). "WB analysis of 4 pairs of matched tumor and normal tissues also suggested notably suppressed TRIM9 protein levels in tumor samples." (PMID 37124931, 2023). "In line with the high expression of TRIM9, the protein level of CEACAM6, Smad2/3 and MMP2 were upregulated in TRIM9 overexpressed tumor tissues." (PMID 37249822, 2023). "The TRIM9 methylation ratio was significantly lower in basal type tumor than in the other intrinsic subtypes, which is consistent with the report that basal type tumors are more globally hypomethylated than the other subtypes." (PMID 26543769, 2015). "In vivo, TRIM9 overexpression reduced tumor growth, rescued by HNRNPU co-expression." (PMID 41050689, 2025). "In addition, reducing of TRIM9 expression significantly abolished the inhibitory effect of miR‐29c‐3p inhibitor on the size of tumour growth and the expression of Ki‐67 in vivo." (PMID 38263865, 2024). "In addition, PCR experiments on clinical tumor samples also demonstrated significantly depressed TRIM9 mRNA expression in the majority of tumor tissue." (PMID 37124931, 2023). "Meanwhile, TRIM9 shRNA-treated KYSE-410 tumor cells demonstrated augmented mobility and invasion." (PMID 37124931, 2023). "Thus, we combined chemotherapeutic MMC with Smad2/3 inhibitor ITD-1 for target therapy in TRIM9-overexpressed tumor model." (PMID 37249822, 2023). "Moreover, immunostaining analysis further demonstrated that recurrent patients exhibited enhanced Smad2/3 expression in tumor tissues, when compared to non-recurrent patients, indicating the potential role of Smad2/3 in TRIM9-assocaited tumor progression." (PMID 37249822, 2023). "DCC is considered a tumor suppressor; downregulation of TRIM9 and TRIM68 in BC may lead to changes in BC, although we did not see the correlation in the mRNA level (Spearman coefficient r = 0.022, 0.043)." (PMID 35928444, 2022). "In addition, cell migration/invasion assay also showed that ZEB1 overexpression vector cotransfection in KYSE-30 cells could alleviate the effects of TRIM9 overexpression vector transfection on tumor cell migration and invasion." (PMID 37124931, 2023).
tumor (continued). "Intriguingly, limited tumor suppressive effects were observed in MMC treated group, which was in line with our in vitro results that TRIM9 reduced chemo-sensitivity." (PMID 37249822, 2023). "In contrast, KYSE-30 cells treated with TRIM9 overexpression vectors exhibited significantly lower levels of IC50, suggesting notably alleviated chemoresistance of the tumor cells." (PMID 37124931, 2023). "Moreover, the integration of single-cell RNA sequencing and spatial transcriptomics in our study provided valuable insights into the cellular heterogeneity and spatial distribution of TRIM9 and HNRNPU within the tumor microenvironment." (PMID 41050689, 2025). "Besides, subsequent exploration suggested that TRIM9 shRNA treatment resulted in increased mRNA and protein expression of stem-like phenotypic biomarkers on tumor cells, including CD133 and CD44, whereas TRIM9 overexpression demonstrated completely opposite effects." (PMID 37124931, 2023). "Next, to determine whether methylation is related to gene expression, we subjected the TRIM9 hypermethylated (n = 10) and hypomethylated tumors (n = 10) to ISH and IHC and found that neither ISH signals nor IHC scores in tumor cells were significantly associated with methylation ratios." (PMID 26543769, 2015). "Results indicated that TRIM9 overexpression tumor cells treated with or without CQ exhibited decreased ZEB1 protein levels, whereas MG132-treated tumor cells demonstrated no such effects." (PMID 37124931, 2023).
cancer (7 papers, 2015 to 2025). A tumor composed of atypical neoplastic, often pleomorphic cells that invade other tissues. "By integrating transcriptomic data and gene co-expression networks, we uncovered that TRIM9 is significantly associated with various cancer-related pathways, highlighting its potential as a key modulator of tumorigenesis." (PMID 41050689, 2025). "Functional experiments confirmed that TRIM9 overexpression inhibited the cell viability, invasiveness, and stem-like phenotype of cancer cells." (PMID 37124931, 2023). "However, TRIM9 is also expressed in macrophages and various forms of cancers." (PMID 38277158, 2024). "Genes such as KIF5A, SOX10, MYL9, TRIM9, MYH11, and SNAP25 are known to play important roles in biological development, suggesting that LRP1B may also be a key factor in cancer." (PMID 40170839, 2025).
infection (2 papers, 2016 to 2022). The state of being infected such as from the introduction of a foreign agent such as serum, vaccine, antigenic substance or organism. "Upon infection with viral DNA or RNA, TRIM9 short isoform undergoes Lys-63-linked auto-polyubiquitination and recruits GSK3β to TBK1, resulting in the activation of the IRF3 signaling pathway." (PMID 27667714, 2016). "In crustaceans, different TRIM proteins have been identified with important functions during pathogen infection, since our first identification of a TRIM9 in Litopenaeus vannamei." (PMID 35281067, 2022).
neurodegenerative disease (2 papers, 2018 to 2023). A disorder of the central nervous system characterized by gradual and progressive loss of neural tissue and neurologic function. "If E3 proteins such as RNF182 and TRIM9, which are specifically expressed in the central nervous system, can be linked to target proteins, then it may be possible to develop therapeutic drugs for neurodegenerative diseases with minimal side effects." (PMID 36726375, 2023).
neurological disease (2 papers, 2019 to 2021). "TRIM9, encoding a brain-specific E3 ubiquitin ligase, has been shown by GO analysis to be involved in the neurological disease and inflammation pathways." (PMID 34646089, 2021).
adenocarcinoma (1 paper, 2021). A common cancer characterized by the presence of malignant glandular cells. "In total, four novel genes, including NPTX1, PCSK1, ASXL3, and TRIM9, were all significantly upregulated in NEPC compared with the adenocarcinoma samples, and these genes were all associated with the neuroactive ligand receptor interaction pathway." (PMID 34646089, 2021).
TRIM9 also shares sentences with these, for which no sentence is quoted: Parkinson disease (3 papers); Uterine leiomyoma (2); Alzheimer disease (1); bladder (1); esophageal tumor (1); lung adenocarcinoma (1); myasthenia gravis (1); prostate carcinoma (1); rectal cancer (1); type 2 diabetes (1).